MYD88 (MYD88 innate immune signal transduction adaptor)
Diseases named in the same sentence as MYD88 in open-access papers (continued):
Sharing a sentence is not in itself a finding about the gene and the disease.
diabetes (continued). "In addition, myeloid cell-specific MyD88-deficiency considerably protected mice from developing STZ-induced T1D and delayed the onset of diabetes in NOD mice." (PMID 41027725, 2025). "It has been observed that mice unresponsive to TLR signals or those with Myd88 deficiency do not develop diabetes." (PMID 38254678, 2024). "Moreover, knockout NOD/Myd88-/-mice in germ-free conditions develop diabetes, which can be countered when defined microbiota communities are transferred." (PMID 38254678, 2024). "MyD88 is a pathway that plays a role in diabetes-related inflammation in the heart and retina." (PMID 39323638, 2024). "Germ-free non-obese diabetic (NOD) mice with MyD88 deficiency developed severe diabetes, but colonization of these mice with defined gut microbiota attenuated diabetes." (PMID 37191444, 2023). "Both Myd88−/− and Trif−/− NOD mice have a different microbiota composition compared with WT NOD mice, resulting in a reduced inflammatory immune response that is associated with reduced diabetes susceptibility." (PMID 35521897, 2022). "Notably, heterozygous MyD88KO/+ NOD mice, which normally develop disease, were shown to be protected from diabetes when they were colonized from birth with the intestinal microbiota of a MyD88-KONOD donor mouse." (PMID 30931309, 2019). "Considering that accumulation of diabetogenic T cells in pancreatic islets is a hallmark of the pathogenesis of T1D, these results indicate that myeloid MyD88 signaling promotes the development of STZ-induced diabetes by negatively regulating Ido expression and Treg induction in draining PLNs." (PMID 29522531, 2018). "These authors used a model of diabetes induced using the drug streptozotocin and identified decreased NFkB and MyD88 activity, along with IRAK-1 phosphorylation, leading to a decrease in circulating chemokines and cytokines in TLR2−/−, compared with wild-type, mice." (PMID 28164040, 2017). "The relationship between RAGE and GLO-1 during diabetes has been reported previously and it has been suggested that upregulation of the enzyme is linked to RAGE-mediated transcriptional activation of Myd88." (PMID 25687235, 2015). "However, germ-free MyD88-null NOD mice develop severe diabetes while colonization of germ-free MyD88-null NOD mice with microbiota mimicking normal human gut microbiota reduces diabetes." (PMID 25628617, 2014). "However, MyD88-dependent pathways were less clearly involved in diabetes-induced alterations in albumin accumulation in the retina or leukocyte-mediated killing of endothelial cells." (PMID 23874797, 2013). "Thus, it seems likely that MyD88-dependent pathways within circulating white blood cells regulate important aspects of the diabetes-induced local inflammatory response and oxidative stress within the retina." (PMID 23874797, 2013). "MyD88-dependent pathways play an important role in the development of diabetes-induced inflammation in the retina, and inhibition of MyD88 might be a novel target to inhibit early abnormalities of diabetic retinopathy and other complications of diabetes." (PMID 23874797, 2013). "Diabetes significantly increased leukostasis in WT mice, and deletion of MyD88 from marrow-derived cells totally inhibited the diabetes-induced increase (the number of leukocytes adhering to retinal vessels in MyD88-/-→WT diabetic mice was not significantly different from that in nondiabetic mice)." (PMID 23874797, 2013). "Hence, diabetes-associated vascular damages through AGE-RAGE interaction are probably mediated by TIRAP and MyD88." (PMID 21829704, 2011). "Additionally, we examined the effect of the genetic invalidation of MyD88 on the development of allergic asthma and spontaneous diabetes." (PMID 20628601, 2010). "The present finding of an unexpected role for MyD88 in preventing diabetes may provide a potential novel target/strategy for treating metabolic syndrome." (PMID 20824098, 2010). "The first interpretation is that MyD88 is mandatory for diabetes development." (PMID 20628601, 2010).
diabetes (continued). "As the activation of c-Jun amino-terminal kinase (JNK) in the liver plays a critical role in the development of diabetes, we next examined whether levels of phosphorylated JNK are altered in MyD88-deficient mice." (PMID 20824098, 2010). "On the other hand, TNF-α would not be involved in HFD-induced diabetes in MyD88-deficient mice, because TNF-α level was attenuated in MyD88-deficient mice fed with HFD." (PMID 20824098, 2010). "Collectively these results indicate that TNF-αis not involved in diabetes observed in MyD88-deficient mice." (PMID 20824098, 2010). "Furthermore, the gnotobiotic-reared NOD Myd88−/− mice were protected from diabetes by exposure to SPF gut flora." (PMID 19357791, 2009). "Furthermore, the transfer of gut microbiota from diabetes-protected MyD88-deficient nonobese diabetic mice reduced insulitis and significantly delayed the onset of diabetes." (PMID 31396097, 2019). "NOD.MyD88LysM-KO, NOD.MyD88CD11c-KO, NOD.TRIFLysM-KO, NOD.TRIFCD11c-KO mice and their littermate controls carrying MyD88 or TRIF floxed alleles but not the respective Cre trangenes were monitored for diabetes development by weekly blood glucose measurements starting from the age of 8–10 weeks." (PMID 29522531, 2018). "MyD88-dependent pathways play an important role in the development of diabetes-induced inflammation in the retina, and inhibition of MyD88 might be a novel target to inhibit early abnormalities of diabetic retinopathy and perhaps other complications of diabetes." (PMID 23874797, 2013). "In the present study, we found MyD88-deficient mice fed a HFD had increased circulating levels of insulin, leptin and cholesterol, as well as liver dysfunction (increased induction of ALT levels, increased activation of JNK and cleavage of PARP), which were linked to the onset of severe diabetes." (PMID 20824098, 2010). "However, to our surprise, we found that MyD88 is involved in protecting against diabetes mellitus." (PMID 20824098, 2010). "In a rat model of type 2 diabetes mellitus, TLR4/MyD88/NF-κB signaling led to the production of tumor necrosis factor-α, interleukin-6, and monocyte chemoattractant protein-1, which caused heart and liver complications." (PMID 39323638, 2024). "Using various knockout animal models, it has been shown that innate signaling proteins such as MyD88 and TRIF, which control microbe-sensing through pattern-recognition receptors, can greatly impact diabetes incidence." (PMID 36059452, 2022). "Several recent reports have elucidated the role of the gut microbiome and its components in the pathogenesis of diabetes and its sequelae, and MyD88-KO mice on a NOD background have decreased inflammation and diabetes development." (PMID 29435463, 2017). "Transfer of microbiota from Myd88-/-NOD mice, which are protected from diabetes, has been shown to reduce insulitis and delay T1DM development in the normal diabetes prone NOD recipient." (PMID 25883945, 2015). "We created MyD88−/−Lnk−/− mice and found that MyD88−/−Lnk−/− as well as WT or MyD88−/− mice did not develop diabetes after low-dose STZ injection." (PMID 41027725, 2025). "When compared to the normal group, the diabetes model group's mRNA expression levels for LBP, TLR4, MyD88, NF-κB, AP-1, and IRF-3 were significantly higher (p < 0.05); after taurine treatment, we discovered that these mRNA levels had decreased significantly (p < 0.05)." (PMID 38560269, 2024). "Diabetes increased TLR4-mediated inflammation, whereas DP inhibited the protein expression of the TLR4 pathway (TLR4, Myd88, IRAK1, and TRAF6) and reduced the mRNA expressions of IL-1β, IL-1α, IL-6, and TNF-α and the protein expressions of TNF-α, IL-1β, and COX-2." (PMID 35463063, 2022). "In addition, deletion of the toll-like receptor (TLR) adaptor protein, MyD88, in SPF NOD mice protects from them diabetes; in contrast, robust autoimmune diabetes is observed in germ-free MyD88−/− NOD mice." (PMID 33810172, 2021).
diabetes (continued). "Evidence for TLR involvement was provided by the finding that knocking out MyD88 (coding for a protein involved in TLR signaling) in non-obese diabetic /diabetes-prone mice prevented the development of diabetes." (PMID 32802088, 2019). "Type 1 diabetes mellitus does not occur in pathogen-free NOD mice lacking MyD88 protein (an adaptor for multiple innate immune receptors that recognize microbial stimuli), and this has been attributed to the presence of commensal microbes." (PMID 28824543, 2017). "This is so since, germ-free MyD88-negative NOD mice develop diabetes, whereas colonization of these germ-free MyD88-negative NOD mice with healthy gut bacterial phyla do not develop type 1 DM." (PMID 28824543, 2017). "The protective effect of MyD88 deficiency requires the presence of the gut microbiome, since mice that were lacking MyD88 NOD readily developed diabetes in a GF facility." (PMID 25682593, 2015). "The MyD88 knockout (KO) effect on diabetes is dependent upon commensal microbes since germ-free MyD88-negative NOD mice develop robust diabetes." (PMID 26347203, 2015). "This suggests that the gut microbiota mediates protection from diabetes in the absence of MyD88 but not in its presence." (PMID 24086519, 2013). "This suggests that inhibition of leukocyte mediated killing of endothelial cells in animals lacking TLR2/4 is mediated via a MyD88-independent pathway, but clearly indicates that MyD88 is a factor in diabetes-induced leukocyte activation." (PMID 23874797, 2013). "Deletion of MyD88 from only marrow-derived cells totally inhibited the endothelial ICAM-1 induction in retinas from diabetic animals, and signaling through both TLR2/4 and IL-1β contributed partially to altered regulation of ICAM-1 in diabetes." (PMID 23874797, 2013). "Of note, the important NK cell activation factor IL-18 is not required for diabetes as MyD88 signaling is necessary to process functional IL-18." (PMID 22558306, 2012). "Those authors found that NOD Myd88−/− mice were protected from diabetes under sterile pathogen free (SPF) conditions but not under gnotobiotic conditions." (PMID 19357791, 2009). "Our data do not contradict the recent finding that the absence of Myd88 leads to changes in the penetrance of diabetes in NOD mice raised in either SPF or gnotobiotic conditions." (PMID 19357791, 2009). "Transplantation of gut microbiota from MyD88-deficient non-obese diabetic mice, which are protected from T1DM development, into NOD mice resulted in a significant reduction in the onset of insulitis and a delay in diabetes onset." (PMID 40422866, 2025). "In addition to DCs, B cells could also be activated by MyD88-mediated signals and could expand T cells via CD40–CD40L interaction in the process for developing diabetes." (PMID 41027725, 2025). "Furthermore, WT recipients transplanted with MyD88−/−Lnk−/− BM cells did not develop diabetes in contrast to those transplanted with Lnk−/− BM cells." (PMID 41027725, 2025). "Moreover, the findings suggest that exercise exerts its beneficial effects through the activation of the irisin signaling pathway, which, in turn, inhibits the TLR4/MyD88/NF-κB pathway, thereby mitigating the exacerbation of hippocampal neuroinflammation and the decreases in AHN induced by diabetes." (PMID 39452118, 2024). "T1D participants with microvascular complications presented lower MYD88 mRNA expression when compared to T1D participants without microvascular complications (P = 0.0008 after adjustment for sex, age, HbA1C, diabetes duration, and use of ACEI, ARB, and statin)." (PMID 32273829, 2020). "It was reported that diabetes development was completely prevented in MyD88−/− NOD mice, whereas the deletion of TLR3 could not suppress diabetes development in NOD mice." (PMID 25343451, 2014).
diabetes (continued). "Since white blood cells play causal roles in the development of diabetic retinopathy, the present study investigates MyD88-dependent processes (involving TLR2/TLR4 and IL-1ß) in leukocytes from diabetic mice, and how these changes affect leukocyte-endothelial interactions in the retina in diabetes." (PMID 23874797, 2013). "Therefore, in the present study, CRAMP may inhibit the activation of colonic MyD88/JNK/NF-κB/NLRP3 signaling pathway, subsequently suppressing the recruitment of IFN-γ+ T cells and their migration to the pancreas in C. rodentium-accelerated diabetes." (PMID 35547774, 2022). "Mice lacking Myd88 (that cannot respond to most TLR signals) do not get diabetes, but NOD.Myd88−/− mice in germ-free conditions do develop diabetes that can be blocked by transfer of defined microbial communities." (PMID 26124756, 2015). "Interestingly, NOD mice lacking the adaptor molecule MyD88 involved in intracellular TLR signalling, were protected from diabetes when kept under normal specific pathogen-free conditions whereas germ-free mutants still developed diabetes." (PMID 24086519, 2013).
atherosclerosis (75 papers, 2007 to 2026). A disease characterized by the build-up of fatty material and calcium deposition in the arterial wall resulting in partial or complete occlusion of the arterial lumen. "Since MyD88 is linked to inflammatory responses, these results underscore the role of lipid patterns in regulating inflammatory pathways associated with atherosclerosis in macrophages." (PMID 39247623, 2024). "There are also data suggesting that the MYD88-dependent production of GM-CSF can cause monocytes to differentiate into inflammatory macrophages, thus promoting atherosclerosis." (PMID 37298199, 2023). "MyD88 deficiency prevents early atherosclerosis, likely by suppressing inflammation resultant from EndMT." (PMID 38268851, 2023). "The role of MyD88 and its association with TLRs in the development of atherosclerosis have been studied in ApoE–/–mice." (PMID 35845572, 2022). "MyD88-deficient mice exhibit a significant decrease in inflammatory cytokines and chemokines in the early stages of atherosclerosis." (PMID 32378144, 2021). "Atherosclerosis-prone ApoE−/− mice with deficiency of TLR4 or MyD88 show attenuation in atherosclerosis development through decreased macrophage recruitment." (PMID 27795867, 2016). "Different outcomes from these studies on endosomal TLR signalling warrant continuing research to fully understand the mechanisms underlying MyD88-independent TRIF signalling in the pathophysiology of atherosclerosis." (PMID 23880853, 2013). "Mice deficient in MyD88 are less prone to atherosclerosis and patients with D299G polymorphism of TLR4 have reduced risk of this disease." (PMID 23305364, 2012). "The relevance of TLR function in atherosclerosis is supported by the observation that a deletion of the MyD88 gene, encoding a pivotal adaptor molecule in the TLR signalling pathway, inhibits atherosclerosis in apoE-/- mice." (PMID 17980027, 2007). "PF may inhibit the inflammatory response via the TLR4/MyD88/NF-κB pathway to attenuate the occurrence of atherosclerosis; therefore, the specific underlying mechanism warrants further study." (PMID 40815470, 2025). "In order to showcase the applicability of this cellular multi-omic platform and also to characterize the lipidome and transcriptome associated with an atherosclerosis protective phenotype of macrophages, we investigated the specific molecular changes in MYD88-KO macrophages versus control cells." (PMID 39247623, 2024). "Therefore, the reasons why MyD88 antagonists were largely studied to combat inflammation and associated diseases such as atherosclerosis are evident." (PMID 39247623, 2024). "Multi-omics can provide valuable insights into the lipidome alterations occurring together with gene expression patterns in MyD88-KO macrophages during the anti-inflammatory state, shedding light on the underlying mechanisms involved in atherosclerosis protection." (PMID 39247623, 2024). "TLR4, TLR2, and MyD88-deficient mice had reduced development of atherosclerosis." (PMID 36363591, 2022). "MyD88 deficiency in endothelial cells results in a moderate reduction in diet-induced adipose macrophage infiltration, and M1 polarization, selective insulin sensitivity in adipose tissue, and amelioration of spontaneous atherosclerosis." (PMID 26959040, 2016). "Owens et al11 recently reported that deficiency of TLR4 or MyD88 reduced both angiotensin II (AngII)–induced atherosclerosis and AAA formation, indicating that innate immune signaling may contribute to the pathogenesis of AAA." (PMID 23537804, 2013). "Interestingly, genetic deficiency of MyD88, known to be associated with a decrease of atherosclerosis development, leads to impaired TH1 differentiation and a switch towards TH2 responses." (PMID 20652007, 2010).